AR (androgen receptor)
Diseases named in the same sentence as AR in open-access papers (continued):
Sharing a sentence is not in itself a finding about the gene and the disease.
Azoospermia (22 papers, 2010 to 2025). Absence of any measurable level of sperm,whereby spermatozoa cannot be observed even after centrifugation of the semen pellet. "The AR NM_000044.6: c.2051G>C mutation in this case is responsible for the phenotype of azoospermia independently of the transactivation activity of AR." (PMID 36159980, 2022). "Among this cohort, two with an AR mutation had undergone sperm analysis that had demonstrated azoospermia (FSH, 89 and 86 IU/L at last presentation)." (PMID 27403927, 2016). "The results of this population-based, case-control study suggested that AR rs1378525568 TT genotype and AR rs137852599 C allele have a protective effect on fertility and may reduce idiopathic azoospermia or severe oligospermia risk." (PMID 35958962, 2022). "Increased AR-CAG repeat length was also associated with azoospermia." (PMID 26962784, 2016). "Studies of complete or specific testicular cell type-specific AR-null mouse models show that spermatogenesis is arrested at the meiosis stage and lowers serum testosterone levels, resulting in azoospermia and infertility." (PMID 38786072, 2024). "CDYL acts as a co-regulator of AR transactivation, and its expression is decreased in the Sertoli cells of human testes from patients with azoospermia." (PMID 38786072, 2024). "Analysis results of these mouse models contribute to elucidating the pathological process and AR signal of human maturation arrest azoospermia." (PMID 38786072, 2024). "Therefore, the novel mutation in LBD of AR may be responsible for MAIS azoospermia." (PMID 36159980, 2022). "Liu et al24 using small sample size found that the AR-CAG repeat length was 30.8 ± 1.1 in group of azoospermia, which was significantly higher than that of fertile control." (PMID 26962784, 2016). "It is possible that ablating AR from the smooth muscle cells of the arterioles only disturbs testicular microcirculation at its most distal parts, resulting in focal areas of azoospermia in these regions." (PMID 21049031, 2010). "Azoospermia is most commonly associated with microdeletions of the AZF gene on the Y chromosome, but mutations in the androgen receptor (AR) gene, important for sex hormone signalling, are also associated with this phenotype." (PMID 20210997, 2010). "In males, AR dysregulation may contribute to spermatogenic arrest and, potentially, azoospermia, whereas splicing abnormalities affecting the AR signaling pathway may be implicated in testicular dysgenesis syndrome." (PMID 40507967, 2025). "In patients with nonobstructive azoospermia, testicular Sertoli cells exhibit differential expression of AR-SVs, which is associated with impaired spermatogenesis." (PMID 37626712, 2023). "Furthermore, a custom panel for detecting the known genes of azoospermia was developed, from which three cases with positive results (two with TEX11 mutation, one with AR mutation) were excluded." (PMID 35495142, 2022). "Mutation analysis of the androgen receptor (AR) gene is suggested in cases of non-obstructive azoospermia and severe oligozoospermia with evidence of androgen insensitivity (high/normal testosterone and high LH)." (PMID 32486230, 2020). "Cell type-specific knockout of AR in Sertoli cells leads to azoospermia in mice." (PMID 20210997, 2010). "We then used real-time RT-PCR to quantitatively analyze the expression levels of AR, SOX9 and AMH in the 23 and 33 patients with obstructive azoospermia with normal spermaotgensis and SCOS, respectively." (PMID 24098470, 2013). "In patients with nonobstructive azoospermia, the secretion of inhibin B, Androgen receptor (AR), Bone morphogenetic protein 4 (BMP4), Stem cell factor (SCF) and other growth factors secreted by Sertoli cells is significantly reduced." (PMID 38001535, 2023).
clear cell renal cell carcinoma (22 papers, 2015 to 2026). "Similar conclusions from previous research suggest that AR protein expression is significantly associated with low-stage, well-differentiated tumors and a favorable prognosis in patients with clear cell renal cell carcinoma." (PMID 41486951, 2026). "The significant association between positive AR staining and favorable tumor features seen in our clear cell carcinomas of the kidney is also in line with previous studies." (PMID 38790919, 2024). "Intriguingly, in the context of clear cell renal cell carcinoma (a sex-biased tumor), a higher androgen receptor expression was associated with decreased lymphatic metastases." (PMID 39061998, 2024). "Clear cell renal cell carcinoma (ccRCC) has gender differences, with the androgen receptor (AR) linked positively with metastasis to the lung." (PMID 33783995, 2021). "CircHIAT1 expression was suppressed by androgen receptor (AR) in clear cell renal cell carcinoma (ccRCC)." (PMID 31526370, 2019). "Upregulated androgen receptor (AR) expression can accelerate the development of clear cell renal cell carcinoma (CCRCC) by inhibiting miR-145." (PMID 30126353, 2018). "To further elucidate the relationship between AR expression and patient prognosis we took advantage of the Cancer Genome Atlas (TCGA) data on clear-cell renal cell carcinoma." (PMID 29108248, 2017). "While the androgen receptor (AR) may influence the progression of clear cell renal cell carcinoma (ccRCC), its role to impact vasculogenic mimicry (VM) to alter the ccRCC progression and metastasis remains obscure." (PMID 33510354, 2021). "A study of the antigen receptor (AR) in clear cell renal cell carcinoma (CCRCC) revealed that AR-mediated suppression of circHIAT1 (hsa_circ_001013) could enhance CCRCC cell invasion and migration via miR-195-5p/29a-3p/29c-3p/Cdc42 signaling." (PMID 32943996, 2020). "In clear cell renal cell carcinoma, AR suppressed circHIAT1 expression by regulating the expression of its host gene (HIAT1) at the transcriptional level, which resulted in deregulation of miR-195-5p/29a-3p/29c-3p, and increased CDC42 to enhance cell migration and invasion." (PMID 31623628, 2019). "Androgen receptor (AR) inhibits circHIAT1 expression, reducing expression of miR-195-5p/29a-3p/29c-3p, thereby increasing CDC42 expression, enhancing migration and invasion of Clear cell renal cell carcinomas (ccRCC)." (PMID 36966306, 2023).
depression (22 papers, 2012 to 2026). "Recent studies reported that depression was observed in 36% of patients with complete androgen insensitivity syndrome due to loss of AR activity." (PMID 31480771, 2019). "The study suggests that AR deficiency may accelerate the development of depression-like behavior in chronically mildly stressed mice." (PMID 34257681, 2021). "While testosterone levels and AR gene polymorphism have been shown to predict specific symptoms of depression in young males, the association of AR mRNA expression in adult male patients with MDD remain unclear." (PMID 31480771, 2019). "In terms of FXAND, 20 PM allele carriers (66.7%) were diagnosed with depression, with the likelihood of depression being significantly reduced for carriers of PM alleles with greater AR-Sb (p = 0.02) or marginally significant for carriers of PM alleles with higher AR-mPCR (p = 0.06)." (PMID 37443745, 2023). "However, a study using a logistic regression analysis with stratification for AR CAG repeat length found that the risk for depression was significantly lower in men with a highly sensitive androgen receptor due to short CAG repeats if their testosterone levels were high." (PMID 36418656, 2022). "Behavioral and reproductive assessments included depression-like behavior tests, sexual behavior, sperm quality, testicular histopathology, steroidogenesis proteins (AR, CYP11A1, StAR), and apoptosis markers (Hsp70, caspase-3, caspase-9)." (PMID 41598271, 2026). "A genetically informed precision medicine approach using genes regulating testosterone levels and androgen receptor sensitivity will likely provide critical insight into the role of testosterone in depression." (PMID 36418656, 2022). "A genetically informed precision medicine approach using genes regulating testosterone levels and androgen receptor sensitivity will likely be essential in gaining critical insight into the role of testosterone in depression." (PMID 36418656, 2022). "Androgen receptor expression has been found to be decreased by 2.7-fold in hypothalamus of men with major depressive disorder compared to male controls." (PMID 36418656, 2022). "Studies have shown that AKT1, VEGFA, ESR1, IL6, and AR play an important role in the treatment of depression." (PMID 34257681, 2021). "Involvement of stress and AR signaling in the onset of depression was investigated in this current study." (PMID 31480771, 2019). "Moreover, genetic variants and the epigenetic profiles of the androgen receptor gene, well-known depression related genes, and HPA axis-related genes were shown to further interact with men’s steroid secretion and thus may further contribute to the proposed male-specific pattern for depression." (PMID 28096796, 2016). "Hit one represents polymorphisms in the AR, BDNF, 5HTTLPR, FKBP5, and NR3C1, which independently increase the risk of developing depression, AUDs, and suicidal behavior in men." (PMID 28096796, 2016). "Some study showed that the expression of estrogen receptor (ER) and androgen receptor (AR) increased in the CRH neurons of PVN in depression patients." (PMID 25887143, 2015). "Indeed, subjects with depression have demonstrated lower androgen receptor mRNA expression in the paraventricular nucleus (men and women, mean age of 67 years)." (PMID 36231806, 2022). "An androgen receptor with higher affinity and sensitivity for testosterone due to shorter CAG repeat length in the presence of low testosterone levels has been associated with depression in men with European or African ancestry." (PMID 36418656, 2022). "Testosterone activated androgen receptor signaling in the hippocampus has been shown to upregulate neurogenesis, which may promote antidepressant responses in depression." (PMID 36418656, 2022).
depression (continued). "Together, these results unify the evidences regarding the anti-depression effects of AR and suggest that AR may have protective roles in antagonizing stress-induced depressive-like behaviors through down-regulation of miR-204 to promote BDNF expression." (PMID 31480771, 2019). "While androgen receptor (AR) and stress may influence the development of the major depressive disorder (MDD), the detailed relationship, however, remains unclear." (PMID 31480771, 2019). "Hypermethylation or hypomethylation of key genes for the development of depression in men, such as the AR, BDNF, 5HTT, FKBP5, and NR3C1 constitute independent risk and resilience factors for depression, AUDs, and suicidal behavior and further interact with the prior described genetic predisposition." (PMID 28096796, 2016). "The androgen receptor may not have important roles in the susceptibility to depression or the positive response to TRT if the androgen receptor has less sensitivity to testosterone due to longer CAG repeats." (PMID 36418656, 2022). "Androgen receptor (AR) may influence the development of major depressive disorder." (PMID 34257681, 2021). "However, the molecular mechanisms of androgen/AR actions on the development and progression of depression remain unclear." (PMID 31480771, 2019). "In 73 adolescent boys with depression defined via a BDI-II score > 13, there was a significant interaction between FT and the number of CAG repeats of the AR regarding depression severity." (PMID 34744823, 2021). "To link the function of AR to the CMS-mediated depressive-like behavior in male mice, we first set up the protocol of CMS model of depression in wild type (WT) mice under CMS in different periods of time, and compared to the control group of non-stressed WT mice by Sucrose preference test." (PMID 31480771, 2019). "Therefore, HF may improve depression symptoms by regulating including but not limited to MAOA, MAOB, AR, CAMK2A, and GAD2." (PMID 34306154, 2021). "While the effect of testosterone on adolescent depression is likely related to its effect on brain morphology and functioning, the relationship between CAG-RL and androgen receptor functioning in the central nervous system is not well-investigated." (PMID 34744823, 2021).
Hyperglycemia (22 papers, 2011 to 2025). An increased concentration of glucose in the blood. "It is worth mentioning that by using QNZ (an NF-κB inhibitor) the hyperglycemia-induced downregulation of AR was blocked, thus underlining the central role of NF-κB in preventing the development of PCa in T2D." (PMID 24058525, 2013). "Hyperglycemia plays an important role in the pathogenesis of diabetic complications associated with vascular and nerve damage by several mechanisms such as increased AR-related polyol pathway flux, increased AGEs formation, and excessive oxidation stress." (PMID 28326319, 2017). "Pharmacological studies have proven that biological activities of AR include immunomodulatory, anti-inflammatory, anti-diabetic effects, anti-viral, anti-tumor, cardioprotection, anti-hyperglycemia, anti-oxidant and anti-aging, with minor side effects." (PMID 39215362, 2024). "From a molecular standpoint, the literature is limited, however, some data indicate hyperglycemia as the cause of this paradoxical impact, with probable mechanisms signaling IGF-1, inflammation, SRF5A2, and AR pathways." (PMID 35399507, 2022). "Most significantly, we uncovered an insulin-independent beneficial role for androgen receptor antagonism in hyperglycemia, mostly by reducing fasting glucose levels." (PMID 30520733, 2018). "Since our in vitro experiments showed that hyperglycemia reduced AR levels we decided to explore the possibility that STZ-DM was affecting AR levels in vivo." (PMID 24058525, 2013). "In the present study we provide first evidence that hyperglycemia downregulates AR through NF-κB activation, and that this inhibitory effect is further increased by TNFα." (PMID 24058525, 2013). "The results showed that QNZ co-treatment was able to block the hyperglycemia-induced downregulation of AR mRNA and protein levels." (PMID 24058525, 2013). "In the present study we found that hyperglycemia downregulates AR through NF-κB activation, and that this inhibitory effect is further increased by TNFα." (PMID 24058525, 2013). "However, in hyperglycemia, hexokinase would be almost saturated especially as blood glucose level is over 11.1 mmol/L; soon after AR has been fully activated, more than 30% glucose enters polyol pathway and is converted to sorbitol." (PMID 29038789, 2017). "Hyperglycemia stimulates AR enzyme, leading to the accumulation of hypertonic sorbitol and subsequent lens osmotic expansion, so any agent that exerts efficient AR inhibitory activity would be potential to prevent the occurrence of diabetic cataract." (PMID 29038789, 2017). "We next wanted to study the effects of hyperglycemia on AR levels using LNCaP cells." (PMID 24058525, 2013). "To examine whether hyperglycemia was able to downregulate AR through NF-κB activation in our in vitro system we performed the following experiments." (PMID 24058525, 2013). "Therefore, further studies addressed to investigating other potential signalling pathways induced by hyperglycemia resulting in AR downregulation independently of NF-κB activation are needed." (PMID 24058525, 2013). "Moreover, AR−/− animals allow the opportunity to investigate the molecular pathways by which AR acts in hyperglycemia." (PMID 23614016, 2013). "The mechanisms underlying hyperglycemia on AR regulation have not been previously reported." (PMID 24058525, 2013). "In this regard, it is possible that the low AR levels due to hyperglycemia, high TNFα levels and low testosterone levels, apart from conferring protection against PCa development could also act as a mechanism for driving the prostate cells towards some degree of androgen independence." (PMID 24058525, 2013). "Finally, we stained the endogenous prostates of control and both groups of diabetic mice to explore whether hyperglycemia also downregulates endogenous AR levels." (PMID 24058525, 2013). "However, in hyperglycemia, modulation of AR expression and activity may contribute to the pathogenesis of glomerular impairment." (PMID 22253613, 2011).
Hyperglycemia (continued). "The underlying anti-fibrotic mechanism of icariin involves the activation of AR/RKIP, thereby inhibiting the MEK/ERK pathway and subsequent renal EndMT triggered by hyperglycemia." (PMID 40533818, 2025). "Our recent work showed that male androgen receptor knockout (ARKO) mice developed high-fat diet (HFD)-dependent sarcopenic abdominal obesity, hyperglycemia, and hepatic steatosis, leading to early death." (PMID 32991827, 2020). "We next measured AR mRNA levels in xenografts from control and STZ-DM mice and we found that hyperglycemia reduces AR mRNA levels in tumors of STZ-DM mice when compared with control mice." (PMID 24058525, 2013). "In conclusion, our results suggest that hyperglycemia and TNF-α play an important role in protecting type 2 diabetic patients against PCa by reducing AR levels via NF-κB activation." (PMID 24058525, 2013). "Moreover, since hyperglycemia is able to activate NF-κB in endothelial cells, pericytes and vascular smooth muscle cells, and NF-κB activation might be involved in AR downregulation, we examined whether hyperglycemia could reduce AR levels through NF-κB activation in LNCaP cells." (PMID 24058525, 2013). "The inhibition of 5α-reductase 2, which converts testosterone into DHT, leads to hyperglycaemia, elevated hepatic glycogen storage, altered GLUT2, IR, and AR expression in the liver of males, pointing to a specific role of androgen/AR signaling in the regulation of glucose metabolism in males." (PMID 34572151, 2021). "Recent studies using pharmacologic inhibitors of AR found anti-inflammatory actions even in the absence of hyperglycemia." (PMID 23614016, 2013).